ALB (albumin)
Diseases named in the same sentence as ALB in open-access papers (continued):
Sharing a sentence is not in itself a finding about the gene and the disease.
diabetes (continued). "In the case of patients with diabetes mellitus, the concentration of antioxidants such as vitamin A and E, albumin and transferrin, among others, decreases." (PMID 36145129, 2022). "In our study, we excluded subjects with a history of diabetes, hypertension, or the use of drugs known to impair or protect against albumin leakage." (PMID 35581242, 2022). "Next, because measuring albumin levels in urine is an essential method for the diagnosis of diabetic nephropathy, we evaluated the feasibility of using luciferin to measure trace albumin levels in the urine of 20 patients with diabetes." (PMID 35955470, 2022). "Other laboratory value-related risk factors investigated in the 14 studies contained serum electrolytes, albumin, blood count, coagulation, diabetes-related laboratory values, and microbiological tests." (PMID 36079114, 2022). "Patients with LAAT/dense SEC had a lower percentage of paroxysmal AF and diabetes mellitus, lower lymphocyte count, and serum albumin, greater NLR, and larger LA diameter." (PMID 35571156, 2022). "This association was independent of variables such as age, sex, race, education level, BMI, history of diabetes, smoking, alcohol consumption, sodium intake, triglycerides, total cholesterol, albumin, eGFR, and serum phosphorus." (PMID 36235758, 2022). "Additional predictors of long-term mortality in our cohort were hemoglobin levels, albumin levels, age, pre-existing diabetes mellitus, and high Norton and Morse scales scores." (PMID 35743568, 2022). "In line with the findings of previous studies, we observed lower mortality rates in the patients with higher serum albumin levels and pre-existing diabetes mellitus." (PMID 35743452, 2022). "In univariate analysis, severe disease was significantly associated with increasing age, being male, diabetes, CKD, and CVD, as well as with low LN ratio, serum albumin, and eGFR." (PMID 35223916, 2022). "Pyridoxamine inhibits the generation of hydroxyl radical from the albumin–Amadori system and thereby protects the albumin–Amadori-induced tryptophan modification and exerts its protective effects on diabetes complications, including diabetic nephropathy." (PMID 36144449, 2022). "When it comes to long-term monitoring of diabetes patients, the measurement of blood albumin levels can be considered as a reference." (PMID 35709212, 2022). "In this study, age, fever, hemoptysis, shortness of breath, hypertension, cardiovascular, diabetes, glucocorticoid, immunoglobulin, HFNC, disease severity, HGB, CRP, ESR and ALB were risk factors for PF, which was in according with previous studies." (PMID 36619759, 2022). "Participants in the highest quartile were more obese and had increased prevalence of diabetes mellitus, thyroid disease, higher levels of fasting glucose and more urinary excretion of albumin." (PMID 36028560, 2022). "The most pronounced beneficial effects of LCD are observed in the context of diabetes, where they promote reductions in glycated albumin and glycemia." (PMID 35811945, 2022). "In our study, according to the level of glycated albumin, glycosylated hemoglobin, and perioperative blood glucose, patients with diabetes mellitus were divided into diabetes mellitus controlled group and diabetes mellitus uncontrolled group." (PMID 35194968, 2022). "Urinary nephrin is podocyte protein can be act as a early predictable and prognostic marker than micro albumin fornephropathy in type 2 diabetes mellitus." (PMID 37701508, 2022). "Urinary Exo-miR-451-5p shows the potential usefulness as a sensitive prognostic biomarker, instead of albumin excretion levels, to serially monitor the early renal damage in diabetes." (PMID 35073973, 2022). "Glycated albumin (GA) is an intermediate‐term marker for monitoring glycemic control (preceding 2–3 weeks) in patients with diabetes mellitus." (PMID 35595963, 2022).
diabetes (continued). "Univariate analysis revealed that the absence of smoking habits, habitual drinking, hypertension or diabetes mellitus, lower albumin levels, white blood cells, and higher GGT levels, were associated with high FIB-4 index." (PMID 36411436, 2022). "Factors independently contributing to dementia in our study included advanced age, female sex, presence of diabetes, elevated pulmonary artery systolic pressure at presentation and a lower serum albumin." (PMID 36462552, 2022). "In the single-variable analyses, beta was significantly negative (95% CI < 0) for female sex, age, body mass index, waist/hip ratio, diabetes, urinary albumin/creatinine ratio, systolic pressure, serum cholesterol, and smoking." (PMID 35276819, 2022). "The main risk factors were the patient's age, hospital stay, operation time, antibiotic use time and glucocorticoid use, complicated diabetes, open injury, mechanical ventilation, serum albumin, and indwelling catheterization." (PMID 35126909, 2022). "The final model included eleven independent predictors: age, sex, diabetes, cardiovascular disease, body mass index, smoking, lipid-lowering drugs, systolic blood pressure, hemoglobin, albumin, and blood urea nitrogen." (PMID 35509033, 2022). "Previously, only in patients with hypertension and diabetes, doctors would pay attention to the patient’s urinary albumin to creatinine ratio, because many studies have shown that proteinuria is independently related to all-cause death." (PMID 34983421, 2022). "Expectedly, patients with higher CatLet score tertiles were older, had higher rates of diabetes, and had lower serum albumin levels and LVEF, which was consistent with our previous studies." (PMID 36211570, 2022). "First, pre-treatment univariate analysis revealed that age ≥ 71 years, diabetes, platelet count < 13.2 × 104/μL, albumin < 3.9 g/dL, AFP ≥ 6.2 ng/mL, FIB 4 index ≥ 3.25, and LSM ≥ 9.2 kPa were significant contributors of HCC occurrence." (PMID 35087141, 2022). "The relationship remained significant after adjusting for albumin, gender, diabetes and immunosuppressant usage." (PMID 35746621, 2022). "These analyses were controlled for age, sex, diabetes, and race and for predialysis serum albumin, phosphorus, and systolic BP." (PMID 35812299, 2022). "In contrast, a number of POPF risk factors have been suggested, such as a soft pancreas, obesity, diabetes mellitus, a lower geriatric nutritional risk index (GNRI), lower albumin levels, blood loss, and an extended operation time." (PMID 36558435, 2022). "Unlike other risk factors, such as age, ASA physical status, diabetes mellitus, inhalation injury and TBSA burned, which were derived by our Cox regression analysis, the RDW/albumin ratio is a modifiable factor in the perioperative period." (PMID 35097135, 2022). "A meta-analysis involving 2860 patients with diabetes demonstrated that TZD significantly decreased levels of urinary albumin." (PMID 35176115, 2022). "Depending on the demographic and clinical factors, Age, Gender, Diabetes, Hypertension, Nephrotic syndrome, 24hUTP, ALB, TG, CHO, SCr, eGFR, immunosuppressant, aPLA2R titer, and IL-35 were included univariate variables." (PMID 35983038, 2022). "A significant association of urinary albumin excretion and CIMT was observed in hypertensive men with diabetes mellitus (DM)." (PMID 36227142, 2022). "The purpose of this study was to explore the effects of sodium-glucose cotransporter-2 (SGLT-2) inhibitors on urine albumin to creatinine ratio (UACR) in type 2 diabetes mellitus (T2DM) patients and to recommend appropriate medication care scheme." (PMID 35910530, 2022). "The NAFLD Fibrosis Score [NFS] incorporates age, body mass index [BMI], the presence of diabetes mellitus or impaired fasting glucose, platelet count, albumin, ALT, and AST." (PMID 35036892, 2022).
diabetes (continued). "This was not entirely surprising, given that the elderly and particularly those with diabetes are most at risk; and our previous study that the prefusion complete spike protein binds AGE/glycated albumin." (PMID 36292212, 2022). "Patient refusal, dirty wound, uncontrolled diabetes, on immunosuppressive drugs, serum albumin less than 3.0 mg/dl.Patients with a history of allergy to study agent." (PMID 36124902, 2022). "Based on these observations, we can postulate that previous modifications in megalin-mediated albumin endocytosis and in the Ang II/AT1R axis in PTECs, i.e, in diabetes and hypertension, are risk factors for the development of severe kidney injury in COVID-19." (PMID 36430671, 2022). "Serum Zn and Se concentrations were positively associated with eGFR, while higher Zn and Se concentrations were linked to better renal survival after adjustment for age, sex, diabetes, albumin, and other comorbidities." (PMID 35893916, 2022). "Then, we used a multivariate Cox model, which included the comet-tail score, NYHA class, hydration status, basal epidemiological (age, sex, BMI, edema, diabetes, vascular access, and so on) and some lab data (hemoglobin, albumin, and phosphorus)." (PMID 36648024, 2022). "The glycation process results in a reduced ability of albumin to act as an endogenous scavenger and transporter protein in diabetes mellitus type 2 (T2DM) patients." (PMID 35563162, 2022). "Elevated glucose levels during long-standing diabetes have been shown to induce structural and functional changes in different proteins in the body, including albumin, globulins, fibrinogen, and collagens." (PMID 36698881, 2022). "In patients with diabetes, albumin is modified in presence of chronic hypoxia formed due to oxidative stress and hyperglycemia, and serum IMA level increases." (PMID 35585936, 2022). "Linoleic acid, an omega-6 PUFA, was significantly lower in subjects with diabetes and positively correlated with both albumin and hemoglobin in subjects with cachexia only." (PMID 35269531, 2022). "Evidence on the relationship between heart rate variability (HRV) and albumin-to-creatinine ratio (ACR) combined with estimated glomerular filtration rate (eGFR) in patients with type 2 diabetes mellitus (T2DM) is rare." (PMID 35846280, 2022). "Among the diabetic patients, scatter plots of mean perfusion area and age, refractive power, duration of diabetes, fasting blood glucose, HbA1c, glycated albumin, and mean VD were drawn, followed by Spearman’s correlation analysis." (PMID 36474199, 2022). "The formula is as follows: −1.675 + (0.037 x age) + (0.094 x BMI) + (1.13 if diabetes present) + (0.99 x (AST/ALT)) – (0.013 x platelets) – (0.66 x albumin)." (PMID 35036892, 2022). "A stronger affinity to glycated/AGE forms of serum albumin would enhance such a virulence effect of coronavirus in those with pre-diabetes and metabolic diseases." (PMID 35456942, 2022). "Further Improvements: In the next step, the measurement should be performed under more realistic conditions, taking for example the human serum albumin with different age, gender and diabetes problems into account." (PMID 35062385, 2022). "There were significant differences in the gender, diabetes, pulmonary infection, albumin, serum creatinine, uric acid, blood urea nitrogen, triglyceride, oliguria, diuretic use, antiplatelet drug use between AKI and no AKI patients (all P < 0.05)." (PMID 35247980, 2022). "Microalbuminuria, defined as a urinary AER 30–299 mg/day (or urine albumin-to-creatinine ratio 30–299 mg/g in spot urine specimens), occurs in 26% and 51% of children and adolescents after 10 and 19 years of diabetes, respectively." (PMID 34913986, 2022). "After adjusting for age, diabetes duration, retinopathy, C-reactive protein, albumin, creatinine, and procalcitonin, a logistic regression analysis identified only age and albumin as independent predictors of death." (PMID 36588684, 2022).
diabetes (continued). "LMM individuals were older, had greater prevalence of diabetes, higher BMI, globulin and triglycerides, lower albumin and AGR." (PMID 35501822, 2022). "Patients with diabetes had higher median urinary albumin-to-creatinine ratio with a higher prevalence of microalbuminuria and macroalbuminuria, but similar eGFR." (PMID 35762322, 2022). "Univariate analysis showed that a history of diabetes, preoperative albumin, preoperative haemoglobin, time from injury to surgery, and operation time were correlated with incision infection (p < 0.05)." (PMID 36514037, 2022). "The strongest risk factors for DR are elevated HbA1c levels, longer duration of diabetes, elevated albumin excretion rate (AER), and higher mean diastolic blood pressure." (PMID 36498694, 2022). "•These data provide the information on associations of urinary pteridines with gender, smoking, alcohol drinking, body mass index, and urinary albumin in patients with diabetes." (PMID 35242903, 2022). "In another cohort, hypertension was found in 38.7% of the patients with hypoalbuminemia compared to 17.1% in patients with normal albumin levels (p < 0.001), and the results were similar for the presence of diabetes (22.6% vs. 5.7%, p < 0.001)." (PMID 36289641, 2022). "Marginal, although not statistically significant, differences between the two subpopulations were noticed with respect to the prevalence of diabetes, glycemia, potassium, albumin, LDL cholesterol and platelet levels (p-value range 0.06–0.10)." (PMID 35888609, 2022). "Statistical differences between control and CKD groups were observed for age, sex, weight, BMI, hypertension, diabetes, hyperlipidemia, blood pressure, cholesterol, occurrence of CV events, creatinine, albumin-to-creatinin ratio, albuminuria, and eGFR." (PMID 34442416, 2021). "Albuminuria, measured as the urinary albumin-to-creatinine ratio, is an important marker for predicting the risk of ESRD in diabetes." (PMID 34884571, 2021). "Undernutrition in chronic kidney disease patients was significantly higher among patients with diabetic nephropathy, patients on stage V chronic kidney disease, recently diagnosed with diabetes mellitus and serum albumin value less than 3.8g/dl." (PMID 34237068, 2021). "Other studies that identified lower serum albumin and protein levels in patients with chronic leg ulcers, these patients also had other chronic illnesses such as sickle cell disease or diabetes mellitus." (PMID 34307096, 2021). "When adjusted for age, sex, diabetes, cardiovascular history, albumin, and creatinine, this finding remained similar (HR: 1.15, 95%-CI: 0.92–1.44)." (PMID 33632160, 2021). "Concerning patient-related risk factors, age > 60 years, presence of > 1 comorbidity (lung disease, cardiopathy, diabetes), smoking status, nutritional status, low albumin level, and low hemoglobin level have to be considered." (PMID 34239804, 2021). "Glycated proteins, such as hemoglobin A1c (HbA1c) or glycated albumin (GA), are important glycemic control markers for diabetes mellitus." (PMID 33572552, 2021). "The mean age was 63.5 ± 13.4 years, 1369 (42.0%) were female, 847 (26.0%) had cardiovascular disease, 2157 (66.1%) had hypertension, 1641 (50.3%) had diabetes, mean WC was 87.8 ± 13.3 cm, and average albumin level was 3.8 ± 0.5 g/dL." (PMID 34945829, 2021). "The negative association was more significant in those people with a diabetes diagnosis based on FPG, with the HbA1c level lower by 0.31% for each 2 g/L increase in albumin (β: −0.31, 95% CI: −0.35 to −0.27, P < 0.0001)." (PMID 34055818, 2021). "In this research, the selected drugs commonly used in diabetes and its comorbidities (gliclazide, cilazapril, atorvastatin, and acetylsalicylic acid) were studied for their interactions with bovine serum albumin—native and glycated." (PMID 34202801, 2021).
diabetes (continued). "In the presence of an increment in urinary albumin excretion, it is mandatory to take action in order to reduce overweight and to control hypertension, diabetes, and dyslipidemia to further prevent GFR reduction." (PMID 34960033, 2021). "According to Medicare (a national health insurance program in the United States), barely half of the diabetes individuals get a urine albumin test." (PMID 34943504, 2021). "Our animal model adequately demonstrated the key features of type 2 pre-diabetes including a >40% increase on body weight, higher blood glucose levels, increased albumin-to-creatine ratio, and renal hypertrophy." (PMID 34884897, 2021). "Higher urinary level of MA, age, CRP, lower level of serum albumin, eGFR ABI, diabetes, cerebral infarction, and CHD were also associated with CCVD, and statin reduced CCVD in Cox multivariate analysis (p<0.05)." (PMID 34707745, 2021). "In particular, a former study indicated significant predictors, including age, sex, body mass index, diabetes mellitus, systolic blood pressure, creatinine, serum albumin or total protein, LV hypertrophy, and coronary artery disease." (PMID 34066464, 2021). "In univariate analysis, the lowest quadriceps muscle thickness tertile, diabetes, history of stroke, history of ischemic heart disease, albumin, blood urea nitrogen, uric acid, and handgrip strength were associated with a higher risk of fall injury." (PMID 34022848, 2021). "A previously developed model of glycated BSA, simulating a non-diabetic state (g10_BSA, albumin exposed to 10 mM glucose) and poorly controlled diabetes (g30_BSA, albumin exposed to 30 mM glucose) was applied in the present study." (PMID 34202801, 2021). "Statistical models were fully adjusted for several factors, including age, sex, hypertension, diabetes, chronic lung disease, lymphocyte and platelet counts, aspartate aminotransferase, total bilirubin, albumin, creatine, C-reactive protein and D-dimer levels." (PMID 34025575, 2021). "Looking at each risk factor individually, BMI data were available for 47,541 (99.2%) THAs, albumin data were available for 25,641 (53.5%) THAs, and tobacco use and diabetes data were available for 47,924 (100%) THAs." (PMID 34277906, 2021). "p.Lys68Gln carriers had a higher BMI, lower insulin secretion, worse diabetes control, and an increased urine albumin/creatinine ratio than p.Arg252His carriers." (PMID 34193236, 2021). "The top eight risk factors for DFU onset when measured by mean decrease accuracy were plasma fibrinogen level, neutrophil percentage and hemoglobin level in whole blood, stroke, eGFR, age, duration of diabetes, and serum albumin level." (PMID 34465375, 2021). "Based on the immunoassay philosophy, glycated albumin, one of the indicators of diabetes, was also quantitatively detected in the real blood samples to assess the diabetes progression with a paper-based sensor." (PMID 34577205, 2021). "In the present study, we examined nutritional indicators in PDAC and confirmed that albumin and lymphocyte count were independent protective nutritional indicators while CA19-9 and diabetes were independent risk factors for PDAC." (PMID 34136406, 2021). "For example, markedly more patients in the wound complication cohort had low preoperative albumin, tumors located in the lower extremity, the presence of diabetes, and resections that required flaps for wound coverage during the index surgery." (PMID 34232931, 2021). "Untreated albuminuria will gradually worsen, turning into clinical severe albuminuria grade A3 (albumin-to-creatinine urine ratio >300 mg/g) at 10–15 years after diabetes diagnosis." (PMID 34198818, 2021). "Microalbuminuria, ranging from 30 to 300 mg/day of urine albumin, is prevalent in patients with hypertension, diabetes, and renal disease." (PMID 34625604, 2021).